TNF (tumor necrosis factor)
Diseases named in the same sentence as TNF in open-access papers (continued):
Sharing a sentence is not in itself a finding about the gene and the disease.
depression (continued). "Similar to the findings in CP/CPPS patients, elevated levels of IL-1α, IL-1β, IL-4, IL-13, and TNF-α were observed in CP/CPPS rat prostates, and these elevated cytokine levels showed a positive trend in their correlation with anxiety, depression, and memory impairment." (PMID 27334333, 2016). "50% of the patients treated with interferon Alfa develop depression and patients with depression had statistically higher blood levels of cytokines like tumor necrosis factor and interleukin 6 than those without depression." (PMID 27453739, 2016). "TNF was not a moderator of the effects of either interpersonal or non-interpersonal stress on later depression outcomes." (PMID 25596176, 2015). "Other studies have reported that serum IL-1β and TNF-α levels were not significantly higher in major depression disorders compared with normal subjects." (PMID 25237578, 2014). "When the subgroup with features of CAD was selected and divided to those with and without depression, there was also a significant difference in serum levels of IL-8 and TNF-α (P < 0.05)." (PMID 25237578, 2014). "Increased IL-1β, IL-6, and TNF-α in post-mortem PFC were also found in teenaged individuals that died by suicide, although in this study not all tissue had come from individuals that had been diagnosed with major depression." (PMID 23675319, 2013). "In particular, serum IL-18 levels, but not that of IL-6 or TNF-α, measured 1 and 7 days after stroke were higher in patients that later developed depression." (PMID 23675319, 2013). "We found significant correlations between fatigue, depression and anxiety on one hand, and TNF-α and sIL-2R, but not CRP or IL-6, on the other hand." (PMID 23082161, 2012). "The main finding of this study in Caucasian patients is that the proinflammatory cytokines IL-6 and TNFα are not significantly increased and the anti-inflammatory cytokine IL-10 is not decreased in perimenopausal women with depression." (PMID 22490187, 2012). "The inflammatory theory of depression is not suitable for perimenopausal depression, since serum concentrations of the proinflammatory cytokines TNFα and IL-6 are not raised." (PMID 22490187, 2012). "Furthermore, patients with higher TNF-α level (> 3 pg/ml, n = 7) had higher mean CES-D depression score than the rest of the sample (p = 0.03)." (PMID 21208443, 2011). "Tumor necrosis factor alpha is a nonspecific, but potent, factor in the development of several psychiatric diseases, including depression and dementia." (PMID 21569380, 2011). "At T0 both patient groups, with and without comorbid depression, showed significantly higher TNF-α serum levels than healthy controls (P = 0.002 for cLBP+DE, P = 0.004 for cLBP)." (PMID 20937108, 2010). "Patients with both cLBP and depressive symptoms improved more in their clinical parameters regarding CES-D scores, pain intensity, R&M scores, MCS scale than those without depression who just gained a greater reduction in TNF-α level and PCS scale." (PMID 20937108, 2010). "Both cLBP patients with (median = 2.51 pg/ml, P = 0.002) and without (median = 2.58 pg/ml, P = 0.004) depression showed significantly higher TNFα serum levels than healthy controls (median = 0 pg/ml)." (PMID 20937109, 2010). "The interaction between TNFα level and pain intensity or depression scores was not statistically significant." (PMID 20937109, 2010). "The single correlation between TNF-α serum level and pain during the previous week was found at T3 in the comorbid group but not in the cLBP group without depression." (PMID 20937108, 2010). "The single correlation between TNF-α serum level and pain in the previous week was found at T3 (P = 0.046; phi coefficient = 0.490) in the comorbid depression group (cLBP+DE), but not in the cLBP group without depression." (PMID 20937108, 2010). "Depression as a comorbidity to chronic low back pain did not influence the serum TNF-α level in the course of six months, but seemed to affect the success of therapy." (PMID 20937108, 2010).
depression (continued). "The findings of this study suggest that depression as a comorbidity to cLBP did not influence the serum TNF-α level during six months' follow-up, but did affect the success of therapy." (PMID 20937108, 2010). "The present study clearly shows that depression as a comorbidity did not influence the TNFα level in cLBP patients." (PMID 20937109, 2010). "We wonder whether the changes in TNF-α level could influence the development of depressive symptoms, if we follow up for six months the course of TNF-α level, depression scores parallel to pain intensity." (PMID 20937108, 2010). "Both evidences processed parallel to the reduction of TNF-α levels, which correlates neither with depression score nor with pain intensity at any time point." (PMID 20937108, 2010). "We did not observe differences of serum concentrations of TNF-α, sTNFRs, leptin, and IL-6 between subgroup A and subgroups B and C. It seems that circulating adipokines did not exert influence on depression levels in obese women." (PMID 19587822, 2009). "We consider TNF and MTHFR to be valid candidate genes for both depression and AUD." (PMID 18822146, 2008). "Mining the Entrez Gene records for TNF and MTHFR via the PDG-ACE algorithm, we found twenty one keywords that are common and significantly over-represented across the gene pair, consistent with interaction between these genes in comorbid AUD with depression." (PMID 18822146, 2008). "Each significantly over-represented keyword identified by PDG-ACE represents one hypothesis on the etiology of a genetic interaction between TNF and MTHFR in depression and AUD." (PMID 18822146, 2008). "In searching PubMed, we found evidence that both TNF and MTHFR have been associated with depression and with ethanol in the literature, but not with the comorbidity of depression with AUD." (PMID 18822146, 2008). "Given evidence of genetic influences on depression and AUD, we refined the hypothesis to include interaction between TNF and MTHFR." (PMID 18822146, 2008). "Given this evidence of interaction between TNF and MTHFR in AUD and depression, and consistent with expected environmental influences on complex diseases, we further refined the hypothesis to include gene-by-environment interaction influencing the comorbidity." (PMID 18822146, 2008). "We tested this hypothesis by searching for candidate genes and found published evidence, via Entrez Gene and PubMed, supporting the roles of TNF and MTHFR in depression and AUD." (PMID 18822146, 2008). "Specifically, we observed that CUMS-induced depression models exhibited profound molecular dysregulation characterized by significant BDNF suppression, pathological EGFR overexpression, ERK2 downregulation, pro-inflammatory JUN elevation, RAF1 repression, and chronic stress-driven TNF upregulation." (PMID 41438694, 2026). "In vivo, a lipopolysaccharide (LPS)-induced mouse model of depression was established to assess the effects of WIS32 intervention on behavioral phenotypes, hippocampal neurochemicals (5-HT and BDNF), and serum pro-inflammatory cytokines (TNF-α, IL-1β, and IL-6)." (PMID 42238885, 2026). "Previous studies have suggested that higher levels of several proinflammatory biomarkers such as C-reactive protein, IL-6 and TNF-α may be related to non-response to antidepressant drugs in people with major depressive disorder." (PMID 40624224, 2025). "Dysregulation of the HPA axis after MI and subsequent depression may be influenced by inflammatory factors, particularly Interleukin (IL)-12A and tumour necrosis factor (TNF)-α, but not IL-1β and IL-6." (PMID 41301929, 2025). "The role of TNF-α in the manifestation of depression was not explored." (PMID 40313235, 2025).
depression (continued). "Chronic systemic inflammation in COPD may also contribute to neuroinflammatory processes that underlie depression, and elevated levels of pro-inflammatory cytokines such as IL1β, IFN-γ, IL-2, and tumor necrosis factor (TNF) have been observed in patients suffering from both COPD and depression." (PMID 41008474, 2025). "Older adults with depression have elevated levels of IL-6 and TNF-α compared to their non-depressed homologs, suggesting that age-related neuroinflammatory changes may play a significant role in the onset and persistence of depressive symptoms in older adults." (PMID 40305200, 2025). "In this model, depression-like behaviors correlate with the release of pro-inflammatory cytokines, including interleukin 1β (IL1β), interleukin 6 (IL6), and tumor necrosis factor α (TNFα), in both the brain and plasma, thereby establishing a connection between inflammation and depressive symptoms." (PMID 40001487, 2025). "However, when patients with depressive disorder were compared with those without depression, significant differences were observed in cytokine response, with higher levels of IL-10, TNF, and TGF-β1 and lower levels of IL-8 for depressive patients." (PMID 40333139, 2025). "Elevated pro-inflammatory cytokines like interleukin-6 (IL-6), interleukin-1β (IL-1β), and tumor necrosis factor-alpha (TNF-α) have been consistently observed in women with PPD, further supporting the inflammatory hypothesis of depression and the involvement of the MGB axis." (PMID 41293186, 2025). "Serum corticosterone levels, depression-like behavior, and hippocampal pathophysiology, including the expression of brain-derived neurotrophic factor (BDNF), precursor BDNF (proBDNF), doublecortin (DCX), NeuN, glial cell activation, and tumor necrosis factor-α (TNF-α), were examined." (PMID 40361157, 2025). "Chronic inflammation, with raised levels of pro-inflammatory cytokines such as IL-6 and TNF-α, and C-reactive protein (CRP), affect the central nervous system—specifically, dopaminergic function in the basal ganglia, which may result in depression, fatigue, and cognitive and motor slowing." (PMID 40487528, 2025). "One study reported a significant increase in the serum levels of TNF-α, IL-1β and IL-6 in patients with AD and depression, compared to AD patients without depression, with strong inverse correlations between the MMSE scores and pro-inflammatory cytokine levels." (PMID 39526037, 2024). "Moreover, the increased TNF-α level in serum was correlated with the non-motor symptoms of PD, including depression, cognitive impairment, and sleep disorders." (PMID 38755545, 2024). "Furthermore, in addition to the interleukin family and tumor necrosis factor, rats in an IFN-α induced depression model displayed heightened central and peripheral inflammatory markers, diminished brain-derived neurotrophic factor, and compromised learning capability." (PMID 39911552, 2024). "In the CUMS model of depression, quercetin significantly reduces the behavioral signs of stress, and raises superoxide dismutase, catalase and GSH levels while reducing lipid peroxidation and attenuating the expression and levels of the proinflammatory markers IL-6, TNF-α, IL-1β, and COX-2." (PMID 39150032, 2024). "Additionally, heightened microglia activation has been observed in the white matter region of the dorsal anterior cingulate gyrus in suicidal patients with depression, although the expression levels of IL-1β, TNF-α, and IL-10 were not elevated." (PMID 39654612, 2024). "In a similar vein, patients diagnosed with various forms of depression often show significantly elevated levels of IL-1β in their cerebrospinal fluid (CSF), serum, or urine, as well as higher TNF-α concentrations in their serum, when compared to non-depressed individuals." (PMID 39684342, 2024).
depression (continued). "Lastly, another intriguing hypothesis is that past studies found a positive relationship between TNF-alpha levels and depression, but not suicidal ideation, the same as we have found in this study with ACTH." (PMID 38737407, 2024). "Furthermore, the secretion of prolactin and estrogen, and interfering with mitogen‐activated protein kinase (MAPK) and tumor necrosis factor (TNF) signaling pathways were mainly involved in the multi‐target therapeutic effects of ZZCD against anxiety and depression." (PMID 37905694, 2024). "In depression, adiponectin may reduce activation of the HPA axis by suppressing TNF-α production." (PMID 39409133, 2024). "There were significant interactions of between-person variance in circulating TNF-alpha (p = 0.05) and IL-1ra (p = 0.04) with group on depression, but these effects were not significant for patients or controls when each group was examined separately (ps > 0.05)." (PMID 37444517, 2023). "In patients with anxiety/depression symptoms, there were 25 (45.5%) cases of steroid resistance, 8 (20%) cases of AZA/6-MP resistance, and 9 (19.6%) cases of primary nonresponse to anti-TNF drugs, all of which were higher than those without anxiety/depression symptoms." (PMID 37547213, 2023). "Furthermore, exploring potential mechanisms involving TNF-α, such as its impact on serotonin regulation, tryptophan metabolism, and the HPA axis, provides valuable insights into the complex relationship between cytokines and depression." (PMID 37967104, 2023). "Thus, IL-6, TNF-α and IFN-γ might represent important biomarkers for targeted treatments in schizophrenia and depression might represent an inflammatory endophenotype of schizophrenia with potential responsiveness to immune-based therapies." (PMID 37723153, 2023). "Studies have shown that inflammatory factors IL-1β, IL-6, TNF-α, and CRP are elevated and anti-inflammatory factors IL-4, IL-8, and IL-10 are decreased in peripheral and cerebrospinal fluid and correlate with patients’ symptoms and disease duration in depression and anxiety." (PMID 36624089, 2023). "Unipolar depression (Major Depressive Disorder—MDD) has generally been found to stimulate a pro-inflammatory Th1 response (IL-1, IL-2, soluble IL-2 receptor (-sIL-2R), IL-6, C-Reactive Protein (CRP), TNF-α, and IFN-γ), with a subsequent increase in tryptophan catabolites (the kynurenine pathway)." (PMID 37510730, 2023). "Over recent years, it has been established those pro-inflammatory cytokines such as IL-1, and IL-6, along with tumor necrosis factor-a (TNF-a), induce true major depressive disorders in physically ill patients with no prior history of mental disorders along with illness symptoms." (PMID 36660532, 2023). "Thus, we hypothesize that the upregulation of TNF-α levels in plasma and PBMCs of depression patients may result from a combined increase of miR-342, a TNF-α promoter, and downregulation of miR-155 and miR-146a, TNF-α negative regulators." (PMID 37575572, 2023). "In addition, this study noted that SIRT1 knock-out upregulated TNF-α expression, which reduced 5-HT concentration and simultaneously activated the activity of IDO, increasing the contents of KYN and QUIN and then inducing depression." (PMID 37239191, 2023). "In this sense and linking once again TNF-α and the S1P pathway in depression models, enhancing endothelial barrier integrity through S1PR stimulation or TNF-α inhibition contributes to the recovery from prolonged learned helplessness depression-like behavior in mice." (PMID 37628815, 2023). "Proinflammatory cytokines (including interleukin-1, interleukin-6, and tumor necrosis factor-α), growth factors such as vascular endothelial growth factor (VEGF), and NF-kB activation are all mediated through the AGE-RAGE signaling pathway, which promotes the onset and severity of depression." (PMID 37745719, 2023).
depression (continued). "However, this could only be shown, probably due to variance issues, when the TNF-α distribution was dichotomized by a median split, although TNF-α and IL-1β shared 31% of the variance in the group with depression." (PMID 36261698, 2022). "The node degrees of IL6, nitric oxide synthase 3 (NOS3), solute carrier family 6 member 4 (SLC6A4), estrogen receptor (ESR1), and tumor necrosis factor (TNF) were greater than 10, suggesting that these targets could play important roles in the effects of AL on depression." (PMID 36431060, 2022). "A combination of elevated IL-6, TNF-α, and CRP provided preferable prediction performance in terms of AUC (0.83) over individual biomarkers, with considerable sensitivity (78.5%) and specificity (77.9%) for depression, but it demanded higher costs and additional time." (PMID 35757220, 2022). "For example, TNF, TLR4, IL-2, BCL-2, etc., are closely related to inflammation, and these targets may be the key targets of Hyp, the main active component of HP, in the treatment of depression." (PMID 36556951, 2022). "Notably, acupuncture significantly alleviated the depression-like behaviors and reversed the high expression of HMGB1, Iba-1, and TNF-α in CRS rats, which indicates the antidepressant effect of acupuncture and provides new experimental evidence for new therapies in the treatment of depression." (PMID 35733802, 2022). "Accordingly, depression may be a predictor of no response or a poor response after 3–6 months of anti-TNF or methotrexate treatment of RA." (PMID 36755665, 2022). "In this study, we found that the CMS protocol increased Iba1 expression as well as TNF-α, IL-1α, and IL-1β levels in the hippocampus or serum, while MOs successfully inhibited this effect in CMS-exposed mice, leading to the attenuation of depression-like symptoms." (PMID 36052143, 2022). "This concern is not unreasonable, considering the recent report that depression-like behavior, pain, and elevated levels of TNF-α in the hippocampus are persistent, even after the resolution of peripheral inflammation or the administration of pain killers in an RA animal model." (PMID 35982301, 2022). "In particular, IL-1 and TNF-α showed a significant positive correlation with the severity of depression, while salivary cortisol showed a negative correlation with the severity of depression in the COPD patients." (PMID 36140234, 2022). "Depression is accompanied by the changes in the levels of inflammatory and trophic factors, including interleukins (IL-1beta, IL-2, IL-6), interferon alpha (IFN-alpha), tumor necrosis factor alpha (TNF-alpha), C-reactive protein (CRP), and brain derived neurotrophic factor (BDNF)." (PMID 35455388, 2022). "first reported the association of cytokine polymorphisms with PSD, showing that patients with polymorphisms of anti-inflammatory cytokines IL-4 and IL-10 rather than pro-inflammatory cytokines TNF-α, IL-1β, IL-6 and IL-8 had an increased propensity to develop depression in the acute phase of stroke." (PMID 36225923, 2022). "Moreover, network pharmacology study showed Shuganjieyu capsule may affect 552 targets as well as MAPK pathway, TNF pathway, PI3K-Akt pathways, and so on in treatment of depression." (PMID 35845579, 2022). "So if a small change in this delicate proinflammatory cytokine/neurotrophin balance would have a substantial effect on depression severity, it could explain why no significant decline in the ratio TNF-α/BDNF is observed." (PMID 34841285, 2021). "The lack of information about the time course of TNF-α in depression could in general explain the huge variety of TNF-α levels in different cohorts of depressed patients reported in the literature." (PMID 34257748, 2021). "There is now evidence that depression is accompanied by activation of the immune-inflammatory response system (IRS) marked by increased levels of pro-inflammatory cytokines, such as interleukin (IL)-1, IL-6, tumor necrosis factor (TNF)-α, and interferon (IFN)-γ in the blood." (PMID 33945102, 2021).